IDO1 (indoleamine 2,3-dioxygenase 1)
Diseases named in the same sentence as IDO1 in open-access papers (continued):
Sharing a sentence is not in itself a finding about the gene and the disease.
blood cancer (1 paper, 2018). "In contrast, IDO1 expression was undetectable in blood cancer cell lines (K562, Jurkat, Raji, and Daudi) with or without IFN-γ treatment." (PMID 29685162, 2018).
head and neck tumours (1 paper, 2022). "Investigations have suggested that CTLA-4 and IDO1 expression levels in head and neck tumours are epigenetically regulated via DNA methylation." (PMID 36405713, 2022). "Some immune checkpoints play a role in the immune escape of head and neck tumours, including PD-1/PD-L1, CTLA-4, and indoleamine 2,3-dioxygenase 1 (IDO1)." (PMID 36405713, 2022).
vasculopathy (1 paper, 2019). "By employing adenovirus-delivered Ido1 gene therapy in renal allografts, the authors showed a beneficial effect on transplant vasculopathy in a rat model of renal chronic transplant dysfunction." (PMID 31089419, 2019).
IDO1 also shares sentences with these, for which no sentence is quoted: Hodgkins lymphoma (7 papers); diabetic retinopathy (6); acute kidney injury (5); multiple myeloma (5); aneurysm (4); renal cell adenocarcinoma (4); renal failure (4); respiratory infection (4); systemic sclerosis (4); allergic asthma (3); central nervous system disorder (3); clear cell renal cell carcinoma (3); gastric adenocarcinoma (3); intestinal diseases (3); mental disorder (3); mesothelioma (3); Miscarriage (3); non-Hodgkin lymphoma (3); penile squamous cell carcinoma (3); renal fibrosis (3); thymoma (3); uterine tumors (3); viral diseases (3); arteriosclerosis (2); atopic dermatitis (2); autism (2); bipolar disorder (2); Cachexia (2); chronic obstructive pulmonary disease (2); chronic periodontitis (2).
A further 188 diseases each share a sentence with IDO1 in 2 papers or fewer.